DNMT1 (DNA methyltransferase 1)
Diseases named in the same sentence as DNMT1 in open-access papers (continued):
Sharing a sentence is not in itself a finding about the gene and the disease.
cancer (continued). "EZH2, an important regulator of cancer gene expression, interacts with class I HDACs, and its protein levels and interaction with DNMT1 are downregulated by HDAC inhibitors." (PMID 33676569, 2021). "The analysis of the expression pattern of PPARγ and DNMT1 in different types of cancer (using TCGA) revealed that both genes are dysregulated." (PMID 34439147, 2021). "Aberrant changes in DNMT1 activity and DNA methylation are commonly observed in cancers and many other diseases." (PMID 33851096, 2021). "In this context, cancer treatment with demethylating agents such as 5-aza-2′-deoxycytidine or knockout of DNMT1 in colon cancer has led to a similar balance state that is found in ESCs." (PMID 33430434, 2021). "UCEC exhibited a significantly higher number of mutations across pan-cancers, analogously TET2, DNMT3B, DNMT3A, and DNMT1 have placed a moderate burden in m5C regulator genes." (PMID 34325709, 2021). "Enforced expression of GATA3 in HCT116 cells inhibited a series of cancer-promoting proteins, DNMT1, SETD1A, SETDB1, FOXM1, MYC, and MSI1." (PMID 34595169, 2021). "The hypermethylation of the CpG islands in TSG promoters, catalyzed by DNMT1, is a significant event in the origin of many cancers." (PMID 33922029, 2021). "Previous studies have validated that DNMT1 negatively regulates SOCS3 expression in several types of cancer cells." (PMID 34691358, 2021). "The increasing role of the UHRF1/DNMT1/HDAC1/G9a complex in the epigenetic silencing of many TSGs in cancer supports the targeting of this multiprotein complex as a valuable approach for developing multitarget single epidrugs." (PMID 33922029, 2021). "Meanwhile, genes regulating DNA methylation, including DNMT1 and DNMT3A, the TET family and IDH1 and IDH2, are themselves frequently mutated in cancer and their mutation status is associated with changes to the cancer epigenome." (PMID 34871444, 2021). "Sirtuin 1 (Sirt1) and Dnmt1 DNA (cytosine-5)-methyltransferase 1 (DNMT1) affect both cell proliferation and differentiation, being associated with several cancer processes, and regulating cell cycle-associated genes." (PMID 34359925, 2021). "Azacitidine is an inhibitor of DNA (cytosine-5)-methyltransferase 1 (DNMT1) used to treat malignant tumors." (PMID 32176725, 2020). "A novel strategy to inhibit DNMT1, using an essential enzyme for cancer cell viability highly expressed in BC, was proposed using DNAzymes." (PMID 32784599, 2020). "In this paper, we investigated the effect of mutations on DNA methylation modification genes such as DNMT1, DNMT3A, MBD1, MBD4, TET1, TET2, and TET3 through a pan-cancer analysis." (PMID 32093698, 2020). "In this context, it has been reported that among epi-miRNAs (e.g., miRNAs that regulate epigenetic factors at post-transcriptional level), miR-148a-3p directly targets DNMT1 in cancer." (PMID 32290440, 2020). "DAC-loaded nanogels decorated with PEG manifested sustained DNMT1 depletion, prolonged cancer cell arrest in the G2/M cell-cycle phase, and significantly enhanced the antiproliferative effect of DAC." (PMID 33287297, 2020). "DNMT1 is abnormally activated in tumor tissues and cancer stem cells and functions by catalyzing DNA methylation." (PMID 32308683, 2020). "In osteosarcomas, CXCL12 was epigenetically reduced by DNMT1 and lead to impair cytotoxic T-cell homing to the cancer cells." (PMID 32340605, 2020). "DNMT1 cooperates with critical genes for radio- and chemoresistance in cancer cells, to regulate promoter methylation of tumor suppressor genes (TSGs)." (PMID 32895373, 2020). "Indeed, the overexpression of DNMT1 has been associated with selective promoter hyper-methylation and mRNA downregulation, as demonstrated in schizophrenic patients, as well as in the context of cancer biology, a pathological condition highly linked to inflammation." (PMID 32854421, 2020).
cancer (continued). "In endometrial cancer, exosomal miR-148b derived from CAFs inhibits EMT and invasion of cancer cells by directly targeting DNMT1, thus regulating cancer metastasis in vitro and in vivo." (PMID 33213510, 2020). "MG98 has been found to efficiently reactivate silenced TSGs via downregulation of DNMT1 in several cancer cell lines at concentrations of 25–76 nM and presented inhibitory effect on proliferation." (PMID 32340605, 2020). "Nevertheless, the role of maintenance methylation in tumor development is controversial, since Dnmt1 can exert oncosuppressor or tumor promoter activity depending on the cancer cell context." (PMID 32806509, 2020). "It has been reported that DNMT1 is important in maintaining cancer stem cells (CSCs) in a self-renewal capability and promoting tumorigenesis, for example, mammary CSCs and leukemia stem cells." (PMID 32308683, 2020). "Since DNMT1 plays a crucial role in cancer, its inhibitor has been proposed as a therapeutic target in many cancers." (PMID 32731382, 2020). "Overexpression of lncRNA NEAT1 enhanced viability of cancer cells in a time-dependent manner, whereas treatment with 5-aza, an inhibitor of DNMT1, abolished the effect of NEAT1 on cell survival." (PMID 32296457, 2020). "Our previous study found that OF is able to induce miR-29b, which suppresses DNMTs (DNMT1, 3A and 3B) in cancer cells." (PMID 31500384, 2019). "Like DNMT1, UHRF1 overexpression has also been found in various cancers and associated with down-regulation of several tumor suppressor genes (TSG) including RB116, p16INK417,18, BRCA119, PPARG20 and KiSS121." (PMID 30696879, 2019). "DNMT1 high expression is observed in almost all cancer types and maintains a higher methylation level." (PMID 31244652, 2019). "In this study, we have compared the effect of 2i on UHRF1 and DNMT1 expression in mESCs and human cancer cells." (PMID 30696879, 2019). "We searched for the co-expressed genes for UHRF1 using this program and found that DNMT1 showed a high co-expression score with UHRF1 in cancer samples and normal tissues." (PMID 30696879, 2019). "Taken together, these data indicated that UHRF1 and DNMT1 are co-expressed in different tissues and cancers." (PMID 30696879, 2019). "As the MEK/ERK pathway is widely activated, as a result of RAS or BRAF mutations and others, in human cancer cells, our finding provides a reasonable explanation for widespread transcriptional overexpression of UHRF1 (DNMT1 as well) in various cancers." (PMID 30696879, 2019). "To test the role of MEK/ERK pathway in transcriptional activation of UHRF1 and DNMT1 further, we also treated 12 different cancer cell lines with PD0325901 for 48 hours." (PMID 30696879, 2019). "We further demonstrated that it is the MEK/ERK pathway that controls a coordinated transcription of UHRF1/DNMT1 in cancer cells." (PMID 30696879, 2019). "For example, in the case of the DNMTs, it would be very useful therapy-wise to know which DNMT is involved in which cancer or stage: is DNMT1 the best target or rather DNMT3A or 3B?" (PMID 31791394, 2019). "In cancer cells, high levels of DNA methyltransferase 1 (DNMT1) and DNA methyltransferase 3A/3B (DNMT3A/3B), as well as suppression of TET, have been detected." (PMID 30283976, 2019). "The strongest predictor of high ITH in both KIRC alone or across several cancer types was the presence of mutations in SETD2, DNMT1 and DNTM3A." (PMID 30897760, 2019). "Together our study reveals distinct regulation of UHRF1/DNMT1 in mESCs and cancer cells and identifies activated MEK/ERK pathway as a driving force for coordinated and aberrant over-expression of UHRF1 and DNMT1 in cancers." (PMID 30696879, 2019).
cancer (continued). "A combined treatment can also be conceived to prevent cancer stem cell resistance to PARPi by adding the DNMT1 and HDAC inhibitors as performed in few preliminary studies." (PMID 30791940, 2019). "IL-6 promotes tumorigenesis by altering DNA methylation in cancer cells, by inducing both the expression of DNMT1 and its nuclear translocation through phosphorylation of its NLS via PI-3K/AKT signaling." (PMID 31557902, 2019). "BCLL11A interacts with DNA methyltransferases 1 (DNMT1), which also contributes to CSCs’ maintenance in various cancers, including breast cancer." (PMID 31861404, 2019). "Our results this far showed that UHRF1 and DNMT1 are co-regulated at the level of transcription in various cancer cell lines via the MEK/ERK pathway." (PMID 30696879, 2019). "Together these data provide evidence that 2i broadly regulates UHRF1 and DNMT1 expression in various cancer cells, and does so primarily at the level of transcription." (PMID 30696879, 2019). "As BRAF and RAS mutations, especially KRAS, broadly occur in cancers, it will be of interest to systematically analyze the relationship between UHRF1/DNMT1 expression and BRAF/RAS mutations." (PMID 30696879, 2019). "El‐Osta reported that the methyltransferases Dnmt1 and Dnmt3b cooperatively maintain DNA methylation and gene silencing in human cancer cells." (PMID 31090214, 2019). "Having established that 2i broadly inhibits UHRF1 and DNMT1 expression in cancer cells, we next explored if GSK3β and/or MEK/ERK pathway were required for UHRF1/DNMT1 expression in cancer cells." (PMID 30696879, 2019). "High expression of DNMT1 is detected in S-phase of the cell cycle and makes DNMT1 a specific target for DNA methylation inhibition in rapidly dividing cancer cells." (PMID 35582723, 2019). "To test if these transcription factors also control UHRF1 and DNMT1 expression in other cancer cells, we carried out the same experiments in A549 cells." (PMID 30696879, 2019). "In contrast to mESCs, 2i-induced downregulation of UHRF1 and DNMT1 in cancer cells cannot be rescued by proteasome inhibitor and occurs primarily at the level of transcription." (PMID 30696879, 2019). "DNMT3B is overexpressed in GC and it cooperates with DNMT1 to silence tumor suppressor genes in cancer." (PMID 31534549, 2019). "Using this program we analyzed the expression correlation between UHRF1 and DNMT1 in different cancer cell lines (brain, pituitary, and prostate) and normal tissues (bone marrow) in Homo sapiens." (PMID 30696879, 2019). "As distinct mechanisms were observed for regulation of UHRF1 and DNMT1 by 2i in mESCs and HCT116 cells, we wondered if and how 2i regulates UHRF1 and DNMT1 in various cancer cells." (PMID 30696879, 2019). "We next attempted to determine if the MEK/ERK pathway is broadly required for elevated expression of UHRF1 and DNMT1 in cancer." (PMID 30696879, 2019). "The mechanism explaining hypermethylation can be interpreted from a study in cancer cells showing that the deletion of RFTS domain makes DNMT1 hyperactive and available for euchromatic binding." (PMID 31091831, 2019). "Exposing cancer cells to gamma irradiation has been reported to decrease the protein levels of DNMT1 and DNMT3b." (PMID 30158986, 2018). "According to previous studies, DNMT1 is important for regulating gene expression through DNA methylation, and many genes related to the various diseases, such as cancer, have been reported to be regulated by DNMT1." (PMID 30266897, 2018). "In our study, as a result of refrained CSCs by ablation of DNMT1, the malignant phenotypes of the bulk cancer cells in KYSE150 and EC109 ESCC cell lines were inhibited, including cell proliferation, colony formation, migration and drug resistance abilities." (PMID 29721170, 2018). "By contrast, specific DNMT1 knockdown normalized breast myofibroblasts and repressed their cancer-promoting properties." (PMID 29416775, 2018).
cancer (continued). "The DNMT1 mRNA was more stable in different CAFs relative to their corresponding TCFs, suggesting the role of cancer cells in slowing-down the DNMT1 mRNA turnover leading to its accumulation in the surrounding fibroblasts." (PMID 29416775, 2018). "We have identified a role for HIF-2α in the hypoxic regulation of the cancer marker CD70 that occurs through DNA methylation mediated by DNMT1 and drives cancer cell proliferation." (PMID 29721188, 2018). "DNMT1 is overexpressed in many types of cancer including MIBC, and it is also a target for chemotherapy." (PMID 30419021, 2018). "This study shows that USP24 mediates p300, NF-κB, DNMT1, and β-TrCP to regulate IL-6 expression, thus affecting cancer metastasis." (PMID 30266897, 2018). "In summary, the present data indicate that DNMT1 plays major roles in the transactivation of breast stromal fibroblasts and the consequent cancer-promoting properties." (PMID 29416775, 2018). "This indicates that DNMT1 knockdown restrains the secretion of several cancer-promoting proteins and inhibits the migration/invasion/proliferation abilities of BSFs." (PMID 29416775, 2018). "In tumor tissues or cancer stem cells, DNMT1 is highly up-regulated, and is required for maintaining the state of cancer stem cells." (PMID 30064482, 2018). "DNMT1-null mouse embryos die soon after implantation and display delayed development and structural abnormalities, and overexpression of DNMT1 has been observed in multiple cancer tissues." (PMID 29621315, 2018). "The PI3K/AKT signaling pathway has been reported to regulate DNMTs such as DNMT1 and DNMT3b at both the RNA and protein level in cancer cells." (PMID 29467020, 2018). "Several studies have demonstrated a correlation between DNMT1 and the classical senescence-related gene p16 in some cancer cells." (PMID 28380423, 2017). "DNMT1 is, the primary enzyme responsible for maintaining CpG methylation leading to gene inactivation, significantly elevated in several types of cancer including RCC." (PMID 28978010, 2017). "The enhanced expression of DNMT1 is responsible for change in the methylation patterns of tumor suppressor genes in cancer." (PMID 28036297, 2017). "Another study in vitro also assessed the potential advantages of DNMT1-targeted inhibition for cancer therapy." (PMID 28938637, 2017). "Recent studies have demonstrated that miR-148a can affect DNA methylation via DNMT1 modulation in various cancers." (PMID 28665977, 2017). "We compared mRNA levels of DNMT1, DNMT3A, total DNMT3B, and DNMT3B variants in cancer tissue with those in matched adjacent normal tissue." (PMID 28160561, 2017). "Inhibition of DNMT1, DNMT3a and DNMT3b has been reported to prevent tumor growth in many types of cancers." (PMID 28926997, 2017). "For example, DNMT1 is required for the maintenance of H3K9 methylation in human cancer cells, and DNMT3A PWWP interacts with H3K36me3 and consequently enhances DNMT3A activity." (PMID 28127428, 2017). "The DNA methylatransferase-1 (DNMT1) enzyme is the principal maintenance DNA methyltransferase in human cancer cells, although cooperation of DNMT1 and DNMT3B is necessary for gene silencing." (PMID 28036297, 2017). "When compared with paired adjacent cancerous samples, DNMT1 expression was also observed up-regulation in cancer in 7 studies with 425 cancers and 425 para-cancerous (p = 0.0004)." (PMID 29221215, 2017). "EZH2- and DNMT1-mediated epigenetic regulation contributed to the growth and progression of different cancer cells." (PMID 28360411, 2017). "Overexpression of HA117 up-regulated DNMT1 expression and subsequent expression of cancer stem cell markers." (PMID 28665981, 2017). "Using TCGA database, we found that the expression of DNMT1 was highly correlated with the risk of GC, as the statistically significant for the difference of DNMT1 expression between the cancer group and the normal group." (PMID 29221215, 2017).
cancer (continued). "From HTR-8/SVneo and JEG-3 cells tested, we showed that SP1 facilitated the expression of DNMT1, which is consistent with previous reports in various human cancers and mouse NIH3T3 cells." (PMID 29163762, 2017). "Human cancer cells with DNMT1 knockout were found to retain their inherited methylation pattern, suggesting maintenance activity by the expressed DNMT3a and DNMT3b." (PMID 28052028, 2017). "Previous studies have examined the associations of DNA methyltransferase 1 (DNMT1) polymorphisms, including single nucleotide polymorphisms rs16999593 (T/C), rs2228611 (G/A), and rs2228612 (A/G), with cancer risk." (PMID 28473984, 2017). "The expression levels of DNMT1 are reportedly elevated in various cancers; reduction of DNMT1 also blocks tumorigenesis." (PMID 28870206, 2017). "To test potential DNMT involvement in VEGFA‐driven miR‐128‐2 repression, and since DNA methyltransferases genes, DNMT3A, DNMT3B, DNMT1, are often coregulated and elevated in cancer stem‐like cells, we assayed all three methyltransferases." (PMID 28179359, 2017). "While miR-148a up-regulation can subsequently down-regulate DNMT1 in cancer cells, it has yet to be examined in PFF cells." (PMID 28665977, 2017). "Since DNMT1 has been reported to be up-regulated in many human cancers, compounds inhibiting DNMT1 are currently under active development." (PMID 29137356, 2017). "DNMT1 inhibition was previously reported to exert a radiosensitizing effect in cancer cells through the repression of DNA repair." (PMID 27525019, 2016). "Several human miRs, including miR-29 family, miR-148, and miR-200b/c have been found to be frequently downregulated in human cancers and lead to increase expression of DNMT1 and DNMT3a/b because they directly target the 3′-UTR of DNMTs." (PMID 27384876, 2016). "While these effects were witnessed in cancer cells, it is likely that IL-6 can regulate DNMT1 in other cell types such as brain cells, particularly during development." (PMID 27462204, 2016). "DNMT1 inhibition has also been reported to sensitize various types of cancer cells to radiation and the mechanism was proposed to correlate with the inhibition of DNA double-strand break (DSB) repair." (PMID 27525019, 2016). "In the HCT-116 cancer cell line, 5-azacytidine downregulates the expression of DNA methyltransferases DNMT1 and DNMT3A." (PMID 27347216, 2016). "Despite this complexity, a notable finding is that both DNMT1 and DNMT3b are required for silencing genes in cancer cells." (PMID 28039441, 2016). "It is noteworthy that the RNA-seq data indicate that both DNMT1 and DNMT3A are also overexpressed in most if not all cancers, consistent with previous observation for coordinated overexpression of DNMT3A, DNMT3B and DNMT1 in cancers." (PMID 27462454, 2016). "Previous studies demonstrates that DNMT1 mediated epigenetic silence of tumor related genes is the major mechanism contributes to carcinogenesis and progression of cancer." (PMID 27286455, 2016). "The anti-cancer effects of curcumin are associated with upregulation of TCF21, mediated by downregulation of DNMT1." (PMID 27894084, 2016). "Aberrant expression of DNMT1 is correlated with progression and prognosis of various cancers, such as lung cancer, hepatocellular carcinoma, pancreatic cancer, and bladder cancer." (PMID 27087738, 2016). "Inhibition of EZH2 and DNA methyltransferase 1 (DNMT1) resulted in increased expression of the Th1-type chemokines in cancer cells, leading to increased trafficking of effector T cells to the tumor site and decreased tumor volume." (PMID 27793053, 2016). "Here, we have shown that activation of pRb causes decreased expression of DNMT1, allowing for increased MEG3 expression and decreased cancer cell growth." (PMID 27832204, 2016). "Curcumin abrogates the catalytic activity of a methyltransferase, DNMT1, thereby affecting the methylation of a number of cancer-related genes." (PMID 27894084, 2016).